HMGB1 (high mobility group box 1)
Diseases named in the same sentence as HMGB1 in open-access papers (continued):
Sharing a sentence is not in itself a finding about the gene and the disease.
tumor (continued). "Positive HMGB1, CC3, and Ki67 expression was significantly higher in tumor tissues than in peritumoral tissues (p <0.01)." (PMID 25986235, 2015). "To identify which receptor was responsible for HMGB1 binding, we pretreated live DU145 tumor cells with anti-TLR4, anti-RAGE or the combination of both antibodies for 30 min prior to addition of recombinant HMGB1." (PMID 26469759, 2015). "HMGB1 in turn activated TLR4 and elevated the pro-tumor factors IL-6 and miR-21, together with other important factors like MMP9 and miR-155, to induce carcinogenesis." (PMID 25923834, 2015). "HMGB1, combined with its receptors RAGE and TLR4, appears to be an attractive target for treatment of tumour angiogenesis via neutralization by specific antibodies." (PMID 26099505, 2015). "Supernatants from DTX-treated DU145 tumor cells, which were shown to contain HMGB1, effectively induced sCLU from newly-plated DU145 tumor cells and protected them from DTX toxicity." (PMID 26469759, 2015). "After local anti-tumor treatment like selective internal radiation therapy (SIRT) or transarterial chemoembolization (TACE), HMGB1 and RAGE also had predictive power and were appropriate markers for therapy response." (PMID 26854151, 2015). "HMGB1 interaction with a functional TLR4 on DCs is required for an efficient cross-presentation of tumor-antigens to T cells and the priming of a tumor-specific T-cell response." (PMID 26500646, 2015). "Patients with high HMGB1 expression were more resistant to CRT, as revealed by lower tumor reduction ratio and lower post-CRT histological tumor regression grade." (PMID 25622595, 2015). "The purpose was to visualize the translocation of HMGB1 from the nucleus to the cytoplasm in dying cells and the induction of sCLU in residual live DU145 tumor cells in such cultures." (PMID 26469759, 2015). "In tumour environment, VEGF-A Ab led to the similar inhibition of angiogenesis, and the increasing secretion of VEGF-A was inhibited by antibodies of ds-HMGB1, TLR4 and RAGE." (PMID 26099505, 2015). "HMGB1 expression markedly increased 1 h after ALA-PDT, compared with untreated tumor tissue, and reached a peak at 6 h before beginning to decline." (PMID 26625309, 2015). "Our results suggest that HSP70, HMGB1, and CRT, particularly in combination, are important to stimulate phenotypic maturation of DCs by ALA-PDT-treated tumor cells." (PMID 26625309, 2015). "Oxidative stress promotes DNA damage and lipid peroxidation, which leads to tumor cell death and release of the “danger signal” HMGB1 (high-mobility group protein 1) that stimulates the innate immune response." (PMID 25909217, 2015). "In this study, we confirmed that both mRNA and protein levels of HMGB1 were significantly higher in BUC tissues and cell lines than in non-tumour cells." (PMID 26239046, 2015). "We cultured DU145 tumor cells in a full monolayer and then added 55 nM of DTX for 24 h, followed by dual immunostaining with anti-HMGB1 and anti-sCLU." (PMID 26469759, 2015). "Importantly, multiple currently-used chemotherapeutic drugs could release HMGB1 from tumor cells." (PMID 26469759, 2015). "In conclusion, HMGB1 mRNA and protein tissue levels in the patients with HCC are significantly higher than in those of para-tumor and normal liver tissues respectively." (PMID 25356587, 2014). "Third, extracellular reduced HMGB1 induces autophagy and tumor growth through AGER/RAGE (advanced glycosylation end product-specific receptor), whereas oxidized HMGB1 induces apoptosis in cancer cells." (PMID 25126737, 2014). "In support of this, recent evidences indicated HMGB1 was co-localized with RAGE, suggesting their potential contribution to cellular migration and tumor invasion." (PMID 25356587, 2014). "HMGB1 mRNA levels in HCC were significantly higher than those in normal (p<0.00001) and para-tumor tissues (p = 0.002) respectively." (PMID 25356587, 2014).
tumor (continued). "We evaluated the HMGB1 expression in patients with HCC (both tumor and para-tumor tissues) and normal liver tissues." (PMID 25356587, 2014). "The results of this meta-analysis suggest that HMGB1 mRNA and protein tissue levels in the patients with HCC are significantly higher than those in para-tumor and normal liver tissues respectively." (PMID 25356587, 2014). "For the first time, we conducted a meta-analysis and evaluated HMGB1 mRNA and protein expression levels in tissues from patients with HCC and normal liver or para-tumor tissues." (PMID 25356587, 2014). "However, the increase of HMGB1 in the extracellular space could drive cancer progression because of its activity as autocrine factor capable of promoting the growth and migration of tumour cells." (PMID 25097859, 2014). "The mechanism by which TLR2 induces tumor suppression is thought to be mediated through tumor-derived HMGB1, which activates TLR2 in dendritic cells in the tumor microenvironment, leading to tumor regression." (PMID 25309546, 2014). "HMGB1 mRNA level in HCC was significantly higher than in normal and para-tumor tissues respectively." (PMID 25356587, 2014). "We detected the strongest expression of HMGB1 in all nuclei of WHO type A and AB epithelial tumor cells." (PMID 24705787, 2014). "The relationship between HMGB1, VEGF-C expression, and various clinicopathological features (tumor size, pT stage, distant metastasis, nodal status, and TNM stage) was analyzed." (PMID 23866030, 2013). "Donnelly and colleagues also demonstrated that MV Edmonston strain induced immunogenic death of melanoma tumor cells, through the secretion of inflammatory cytokines (IL-6, IL-8 and type I IFN) and chemokines (RANTES and HMGB1) in an MV dose-dependent manner." (PMID 24832799, 2013). "High mobility group box 1 (HMGB1) and HMGB2 overexpression has been observed in several human tumor types, and is involved in cancer progression and prognosis." (PMID 23426143, 2013). "In addition, p65 in epithelial nuclei was negatively correlated with HMGB1 in the epithelial intercellular spaces (r = -0.1641, P > 0.05), and was negatively correlated with HMGB1 in the inflammatory cells in normal skin and various tumor types (r = -0.0452, P > 0.05)." (PMID 23803172, 2013). "Extracellular HMGB1 can induce a variety of cellular responses, including the expression of proinflammatory mediators, such as tumor necrosis factor-α (TNF-α), tumor metastasis, and the maturation of dendritic cells." (PMID 22563397, 2012). "By RT-PCR and Western blot, the levels of HMGB1 mRNA and protein were significantly higher in HCC, compared to that in para-tumor (p < 0.001) and normal tissue (p < 0.001)." (PMID 22747650, 2012). "Univariate analysis showed that tumor size (p = 0.004), tumor number (p < 0.001), tumor encapsulation (p = 0.011), TNM stage (p = 0.001) and expression of HMGB1 (p = 0.004) were prognostic factors for disease-free survival." (PMID 22747650, 2012). "Depletion of HMGB1 from dying tumor cells abolishes the TLR4-dependent, DC-mediated presentation of antigens from dying tumor cells in vitro and in vivo." (PMID 23251389, 2012). "In conclusion, wogonin can enhance the immunity of tumor cell vaccine, in which ER stress activated AKT signaling pathway mediated calreticulin/Annexin A1 translocation and/or HMGB1/ATP release are involved." (PMID 23251389, 2012). "HMGB1 is able to bind to the toll-like receptor 4 (TLR4) on DC, which allows tumor-derived antigens to be processed and presented along with MHC and costimulatory molecules on the surface of DC." (PMID 22927872, 2012). "Univariate analysis showed that the overall survival was directly influenced by tumor size (p = 0.005), tumor number (p = 0.003), TNM stage (p = 0.004), and expression of HMGB1 (p = 0.008)." (PMID 22747650, 2012). "The DAMP, HMGB1, has been found to be upregulated in some carcinomas in which it activates TLRs, including TLR2, on immune cells and enhances tumour progression." (PMID 21179035, 2011).
tumor (continued). "HMGB1 is able to bind to the TLR4 receptor on DC, which allows tumor-derived antigens to be processed and presented along with MHC and costimulatory molecules on the surface of DC." (PMID 22162710, 2011). "An interesting recent study found that the release of HMGB1, a TLR4 agonist, from dying tumor cells stimulated dendritic cells to initiate an adjuvant anti-tumor immune response in a TLR4 dependent fashion." (PMID 22069563, 2010). "HMGB1 can activate a series of signaling components, including mitogen-activated protein kinases (MAPKs) and AKT, which play an important role in tumor growth and inflammation, through binding to different surface receptors, such as RAGE and TLR2/4." (PMID 21106117, 2010). "The log-rank test was used to compare the level of HMGB1 with the density of CD3+ and CD45RO+ cells within the tumor." (PMID 20846416, 2010). "The generation of an immunogenic tumor cell death through the induction of calreticulin, HSP, release of inflammatory mediators, proinflammatory cytokines or HMGB1 will favor the recognition of tumor cell antigens by DC, NK, and T cells." (PMID 19272170, 2009). "In vivo experiments demonstrated that HMGB1 knockdown reduced distal-tumor rejection by 60%, whereas CRT knockdown reduced it by only 20%, indicating that HMGB1 release may dominate proton-induced ICD." (PMID 41641047, 2026). "We have shown that three TREM-1 ligands, Tag7, Hsp70, and HMGB1 proteins, not only stimulate the production of pro-inflammatory cytokines but also induce the activation of cytotoxic lymphocytes against MHC-negative tumor cells." (PMID 40362307, 2025). "We also identified other genes with well-established functions in T cells exhibiting novel differentially spliced isoforms along these lineages, including the tumor-reactive T-cell marker integrin subunit alpha E (ITGAE) and the proinflammatory cytokine high mobility group box 1 (HMGB1)." (PMID 41273175, 2025). "In addition, ATP drives DC maturation and recruits CTLs to the tumor site by binding to the purine receptor P2RX7; and HMGB1 activates Toll-like receptor 4 (TLR4) to enhance pro-inflammatory signaling to accelerate the ICD process." (PMID 40535125, 2025). "This synergy is critical for overcoming cold tumor resistance: Cuproptosis-induced DAMPs (ATP/HMGB1) recruit dendritic cells and CD8+ T cells, while ferroptosis further enhance tumor antigen presentation and T-cell infiltration, collectively reprogramming immunosuppressive microenvironments." (PMID 40963914, 2025). "Western blot analysis further revealed that the levels of cleaved Caspase-3 and N-GSDME in tumor cells were markedly elevated after infection with ADVNE or ADVPPE, whereas the HMGB1 levels decreased and LDH release increased, all of which are indicators of pyroptosis." (PMID 40082916, 2025). "HMGB1 has been identified as an important regulator of YAP activation in the extracellular fluid, which induces YAP nuclear translocation leading to cell migration, proliferation, and tumor growth." (PMID 41109352, 2025). "The selective TLR2 inhibitor CU-CPT22 effectively blocked DAMP-induced signaling (e.g., HMGB1 release after chemotherapy), synergizing with DOXO to suppress tumor growth, reduce CSC frequency, and remodel the TME by decreasing Tregs and MDSCs while enhancing CD8+ T cells and M1 macrophages." (PMID 41375047, 2025). "Oncolytic viruses (such as T-VEC) selectively lyse tumor cells to release DAMPs (such as CRT, HMGB1) and viral nucleic acids, triggering strong immunogenic cell death (ICD) and activating the cGAS-STING pathway, inducing a “viral mimic” state to enhance antitumor immunity." (PMID 41293424, 2025). "Similarly, low-dose gemcitabine treatment not only increases the exposure of HMGB1 but also upregulates NKG2D ligands and activates NK cells, thereby improving patients’ anti-tumor immunity." (PMID 40297580, 2025).
tumor (continued). "To investigate whether Vpr peptides can induce ICD in tumor cells, we used three tumor cell lines with different immunogenicity, MC38, B16F10, and LLC, and evaluated the three hallmarks of ICD, namely, CRT, ATP, and HMGB1 after Vpr peptide treatment." (PMID 40733687, 2025). "Under stress, tumor cells release DAMP molecules (CRT, HMGB1, ATP, and type I IFN)." (PMID 40535125, 2025). "In particular, tumor tissue from the treated animals showed clear signs of an anti-inflammatory response, including decreased expression of the inflammatory mediators COX-2 and HMGB1 and an increase in necrotic areas." (PMID 40937999, 2025). "VEGF and TGF-β1 capture essential aspects of tumor angiogenesis, hypoxia signaling, and stromal remodeling, whereas danger signals such as HSP90, HMGB1 and S100A9 report on cellular stress, necrosis, and innate immune activation that shape the tumor microenvironment." (PMID 41009692, 2025). "Additional DE and PTM overlapping pathways, including HMGB1 signaling, the regulation of the epithelial–mesenchymal transition (EMT) by growth factors, and IL-4 and IL-13 signaling, indicated the broader impact of RONS on the tumor microenvironment." (PMID 39857768, 2025). "Furthermore, HMGB1 functions as an immune adjuvant by triggering immune activation via TLR4 binding, thereby potentiating detection and destruction of tumor cells by immune cells." (PMID 41354099, 2025). "Thus, addressing HMGB1/RAGE interaction in immune cells such as macrophages and microglia is beneficial to reduce harmful inflammation and impede tumor progression." (PMID 41226481, 2025). "Furthermore, PTT and CDT-induced immunogenic cell death of tumor cells promoted anti-tumor immunity by exposing CRT, HMGB1, and ATP." (PMID 40365286, 2025). "HMGB1 and S100A9, as immune-related DAMPs, may increase transiently after immune checkpoint blockade or chemotherapy due to treatment-induced tumor cell death and immune activation." (PMID 41009692, 2025). "Extracellular HMGB1 has been shown to interact with multiple cell surface receptors, most notably, receptor for advanced glycation end products (RAGE) and Toll-like receptor 4 (TLR4), to promote inflammation and tumor growth." (PMID 41109352, 2025). "Inhibition of circ_0005909 reduced tumor growth in vivo and restricted cell viability, colony formation, migration, invasion, and EMT in vitro, suggesting that it inhibits OS progression by downregulating HMGB1 via miR-936." (PMID 41296391, 2025). "We therefore hypothesized that GCD stimulates HMGB1 release and CRT surface expression, promotes DCs maturation, and ultimately enhances CD8+ T cell infiltration and tumor clearance." (PMID 40994449, 2025). "In summary, HMGB1 activates multiple inflammatory factors in TME by activating signaling pathways such as RAGE, TLR4, and PI3K, thereby promoting tumor growth, facilitating cellular invasion and metastatic spread, while concurrently contributing to therapeutic resistance in cancer treatment." (PMID 40969278, 2025). "The relationship between HMGB1 and pyroptosis in cancer therapy presents a complex paradox, wherein this DAMP can function as either an antagonist or protagonist of treatment efficacy, largely determined by contextual factors within the tumor microenvironment." (PMID 41465435, 2025). "Further exploration revealed that the downregulation of HMGB1 expression effectively inhibited the NF-κB/p65 and its binding activity to DNA, thereby reducing the expression of vascular endothelial growth factor C (VEGF-C) and impeding tumor angiogenesis." (PMID 40877572, 2025). "Moreover, in breast cancer, the activation of pyroptosis leads to the release of high mobility group box 1 protein (HMGB1), which stimulates the TLR4 pathway in TAMs and facilitates the secretion of IL-1β, thereby supporting tumor progression and metastasis." (PMID 40427552, 2025).
tumor (continued). "We also found that HMGB1, a TLR4 agonist that can induce IL-24, is highly upregulated in calcipotriol-treated tumor cells in a CD4+ T cell–dependent manner, suggesting that it may contribute to IL-24 induction in macrophages." (PMID 39782693, 2025). "High Mobility Group Box 1 (HMGB1), released by necrotic and activated immune cells, triggers NETosis via TLR4, RAGE, and MAPK signaling, and in cancer settings, also engages RIPK1-TNF signaling to couple NETs with tumor progression." (PMID 41335221, 2025). "Calreticulin, ATP, and HMGB1 bind to CD91, P2RX7, and TLR4, respectively, facilitating dendritic cell (DC) recruitment into the tumor bed (by ATP), the phagocytosis of tumor antigens by DCs (enhanced by CRT), and an optimal antigen presentation to T cells (stimulated by calreticulin and HMGB1)." (PMID 40313247, 2025). "Concurrently, HMGB1 facilitates myeloid‐derived suppressor cell (MDSC) differentiation, recruitment, and activation, amplifying immunosuppression and impairing effector T cell‐mediated cytotoxicity against tumor cells." (PMID 41354099, 2025). "When tumor cells were treated with docetaxel, neither ATP nor high-mobility group box 1 (HMGB1) production nor cell death was seen." (PMID 40098955, 2025). "Generally, ferroptosis is an inflammatory form of cell death associated with the release of DAMPs, such as high‐mobility group box 1 (HMGB1) and DNA or lipid oxidation products, such as 4‐hydroxynonenal (4‐HNE), oxPLs, LTB4, LTC4, LTD4, and PGE2 during tissue damage or tumor treatment." (PMID 40919133, 2025). "Hypoxic conditions promote HMGB1 release from necrotic tumor cells, which in turn recruits M2-like macrophages and creates an IL-10 rich milieu through RAGE signaling, ultimately facilitating tumor growth and metastasis." (PMID 41465435, 2025). "Further assessment demonstrated that the expression of necroptosis-related genes, including FADD, MLKL, TLR2, PGAM, HMGB1, CXCL 1, TRAF2, and EZH2, was elevated in tumor tissue, while FAS, RIPK1, RIPK3, TLR3, TNFRSF, ALDH2, and NDRG2 were upregulated in normal intestinal tissues." (PMID 40959081, 2025). "In LUAD, FAM72B and HMGB1 may jointly activate the PI3K/AKT signaling pathway, thereby promoting the proliferation and survival of tumor cells." (PMID 41153357, 2025). "Therefore, A more profound comprehension of HMGB1’s function within the TME can be achieved and tumor immunity will help us better develop novel tumor immunotherapy strategies targeting HMGB1." (PMID 40969278, 2025). "This section focuses on how OV-induced ER stress and reactive oxygen species (ROS) regulate tumor cell immunogenicity, key DAMP (CRT, ATP, HMGB1) mechanisms, and how OV-specific pathways (e.g., PERK/eIF2α-mediated ER stress) complement conventional ICD induction [81,]." (PMID 41314288, 2025). "In addition, IGV visualization confirmed significant enrichment of eccDNA at genomic loci of tumor-related genes such as FLT3, RUNX1, CD33, and HMGB1." (PMID 41278279, 2025). "Additionally, TDEs carrying high mobility group protein B1 (HMGB1) have been reported to trigger the differentiation of TIM-1+ Bregs, which suppress the cytotoxic activity of CD8+ T cells and support tumor survival and metastasis." (PMID 40564075, 2025). "This duality underscores that the functional outcome of the autophagy-HMGB1 axis is not fixed but is determined by the biological context, including the cell type, the nature of the stressor, and the state of the tumor immune microenvironment." (PMID 41465435, 2025). "HMGB1 activates the ERK1/2 signaling pathway via RAGE, promoting tumor growth and metastasis." (PMID 40852041, 2025).